CASP2 (caspase 2)
Diseases named in the same sentence as CASP2 in open-access papers (continued):
Sharing a sentence is not in itself a finding about the gene and the disease.
fatty liver disease (6 papers, 2016 to 2026). A reversible condition wherein large vacuoles of triglyceride fat accumulate in liver cells via the process of steatosis. "This has led to development of caspase-2 inhibitors as a means to block diet-induced pathogenic progression of fatty liver disease and HCC." (PMID 41477850, 2026). "Caspase-2-deficient mice fed a Western diet were protected from abdominal fat deposition, diabetes mellitus, dyslipidemia and hepatic steatosis." (PMID 26890135, 2016). "Phosphorylated IRE1α can induce the expression of XBP1s and caspase-2, leading to liver steatosis, hepatocyte damage, and insulin resistance (IR)." (PMID 38638434, 2024). "This interrelation of caspase-2 and liver steatosis was first proposed based on high caspase-2 levels in patients with severe nonalcoholic steatohepatitis (NASH)." (PMID 32415279, 2020). "Taken together, these studies show that caspase-2 is transcriptionally upregulated in these pathologic conditions and promotes progression of fatty liver diseases." (PMID 32415279, 2020). "To clarify the role of caspases in SREBP regulation, we focused on upstream caspase-2, reported to play a role in models of fatty liver disease and in NAFLD4,19." (PMID 31296846, 2019). "Recent studies targeting caspase-2 by either gene ablation or using pharmacological inhibition demonstrated beneficial effects against diet-induced fatty liver in mice." (PMID 31296846, 2019). "Recent studies have revealed an important role of caspase-2 in models of fatty liver disease and in lipoapoptosis." (PMID 31296846, 2019). "Together, these findings demonstrate that while younger caspase-2-deficient mice show some protection from hepatic steatosis, loss of caspase-2 does not prevent age-related steatosis incidence or severity." (PMID 41477850, 2026). "This suggests that LJ3a and LJ2a should be further investigated and optimized for in vivo activity to determine if selective Casp2 inhibitors could offer an effective approach to the prevention or treatment of fatty liver diseases." (PMID 36379916, 2022). "Finally, these findings clearly render manipulation of caspase-2 activity promising for therapeutic intervention in fatty liver diseases but also neurodegenerative disorders and osteoporosis." (PMID 32415279, 2020). "Our data suggest that caspase-2 catalytic activity is partly required for its function in fat metabolism, with Casp2C320S mice having reduced fat accumulation in adipose tissue (both gWAT and dWAT) and reduced age-related liver steatosis incidence at 12 months." (PMID 41477850, 2026). "Strikingly, all studies revealed that lack of caspase-2 is highly protective against fatty liver diseases, independent of the model used." (PMID 32415279, 2020). "Indeed, caspase-2-deficient mice were not protected from hepatic steatosis when fed MCD diet, a model in which hepatic steatosis is a consequence of reduced hepatic lipid export, rather than increased import of adipose-derived NEFAs." (PMID 26890135, 2016).
non-alcoholic fatty liver disease (6 papers, 2016 to 2024). "Caspase-2 has also been implicated in obesity, metabolism, and the development of non-alcoholic fatty liver disease." (PMID 33425918, 2020). "Caspase-2 deficiency protected mice from diet-induced obesity, metabolic syndrome and nonalcoholic fatty liver disease." (PMID 26890135, 2016). "Evidence suggests that caspase-2 deficiency protects mice from diet-induced obesity, metabolic syndrome, and non-alcoholic fatty liver disease, which has led to speculation that caspase-2 activity in NASH is beyond apoptosis." (PMID 39625520, 2024). "Furthermore, it has been demonstrated that loss of caspase-2 significantly improves energy metabolism and reduces weight gain in mice on a high-fat diet that is associated with reduced incidence of non-alcoholic fatty liver disease (NAFLD) progression." (PMID 33854186, 2021). "More recently, it was suggested that Casp2 activation is a critical mediator of the transition from benign non-alcoholic fatty liver disease (NAFLD) to NASH." (PMID 36379916, 2022). "Further, caspase-2 is required for the progression from non-alcoholic fatty liver disease to non-alcoholic steatohepatitis, which is considered a risk factor for further liver damage that promotes hepatocellular carcinoma." (PMID 33425918, 2020). "Given the relationship between non-alcoholic fatty liver disease and liver cancer, it is interesting to speculate that via this S1P/SREBP mechanism, caspase-2 could ultimately be potentiating the risk of liver cancer." (PMID 33425918, 2020).
non-alcoholic steatohepatitis (6 papers, 2019 to 2025). "At the hepatic level, Casp2 plays an essential role in the pathogenesis of nonalcoholic steatohepatitis (NASH)." (PMID 36379916, 2022). "Still on HCC, Michael Karin (La Jolla, USA) presented a novel substrate of caspase 2 promoting steatosis and nonalcoholic steatohepatitis progression, identifying in caspase 2 a new target to prevent and treat these diseases." (PMID 31641107, 2019). "Interestingly, a previous study showed that in hepatocytes, caspase-2 activated SREBP2 by cleaving S1P and that genetic and pharmacologic inhibition of caspase-2 prevented liver steatosis and non-alcoholic steatohepatitis, which are caused by chronic inflammation, by suppressing SREBP2 activation." (PMID 36776855, 2023). "In patients with non-alcoholic steatohepatitis (NASH) and corresponding animal models, there is a notable correlation between elevated levels of the microRNA miR-21 and increased levels of caspase-2 in hepatic tissues." (PMID 40362504, 2025). "On the other hand, caspase-2 expression is linked with the apoptotic cell death in non-alcoholic fatty liver disease (NAFLD) and non-alcoholic steatohepatitis (NASH)." (PMID 36171196, 2022).
Obesity (6 papers, 2016 to 2026). Accumulation of substantial excess body fat. "Loss of caspase-2 has been shown to protect young mice from high-fat or high-fructose diet–induced obesity and hepatosteatosis." (PMID 41477850, 2026). "We show that caspase-2 deficiency protects from the development of HFD-induced obesity, NAFLD and insulin resistance." (PMID 29072701, 2017). "Nevertheless, the current study provides compelling novel evidence that caspase-2 is a potential target to correct obesity and its associated comorbidities: metabolic syndrome, insulin resistance/T2DM and NAFLD." (PMID 26890135, 2016). "In accordance to recent findings, caspase-2 promotes obesity, the metabolic syndrome and non-alcoholic fatty liver disease and for that reason may become a potential target to correct obesity and its associated comorbidities." (PMID 34034759, 2021). "Interestingly, caspase-2-deficient mice fed a high-fat diet were protected from the development of obesity and associated phenotypes like diabetes and hepatic steatosis." (PMID 33425918, 2020). "In addition, we show that caspase-2 deficiency protects from the development of HFD-induced obesity, insulin resistance and NAFLD." (PMID 29072701, 2017). "This would explain why caspase-2 deficiency results in favourable glucose homeostasis and protection from HFD-induced obesity while paradoxically increasing their susceptibility to oxidative stress-induced damage and premature ageing." (PMID 29072701, 2017). "This suggests that iBAT activity is not altered by caspase-2 deficiency and does not contribute to the shift in fuel choice or protection from obesity." (PMID 29072701, 2017). "In addition, we provide further evidence to support a direct role for caspase-2 in adipocyte biology, fat expansion and its potential as a therapeutic target from the treatment of obesity and metabolic disease." (PMID 29072701, 2017). "Thus, modulating caspase-2 activity is an appealing therapeutic approach for obesity and related metabolic syndrome pathology, including NAFLD." (PMID 26890135, 2016). "Combined, these findings indicate that caspase-2 is involved in the maintenance of adipocyte size, function and glucose homeostasis and importantly that caspase-2 deficiency can improve adipose function and protects from HFD-induced obesity, NAFLD and fatty liver." (PMID 29072701, 2017).
ovarian carcinoma (6 papers, 2013 to 2024). A malignant neoplasm originating from the surface ovarian epithelium. "Noteworthy, CRISPR-Cas9 targeting of caspase-2 in human ovarian carcinomas cells enhanced phosphorylation of RIPK1 and MLKL, indicating caspase-2 as a negative regulator of necroptotic cell death to be an important candidate in therapeutic applications." (PMID 39075259, 2024). "In the miR-383/CASP2 pathway, the caspase-2 (CASP2) gene has been identified as a miR-383 target in epithelial ovarian cancer (EOC)." (PMID 36313570, 2022). "Rottlerin inhibited the activation of caspase-2 via ubiquitin proteasome-mediated pathway, resulting in cell apoptosis in HeLa cells and ovarian cancer cells." (PMID 27582552, 2016). "Together, the data indicate that caspase-2 and caspase-3 independent cell death was involved in both the parental and paclitaxel-resistant ovarian cancer cells; the predominant cell death pathway was through apoptosis in parental cells, and mitotic catastrophe in resistant ovarian cancer cells." (PMID 23762410, 2013). "To this point, we used HEK293T cells and ovarian cancer CAOV-4 cells, in which caspase-2 plays an essential role in DNA damage-induced apoptosis." (PMID 33011746, 2020).
dementia (5 papers, 2016 to 2022). Loss of intellectual abilities interfering with an individual's social and occupational functions. "In this study, we report the novel finding that the Casp2-generated tau fragment Δtau314 is associated with dementia in Lewy body diseases." (PMID 31362787, 2019). "Our results suggest a mechanism for the synaptic dysfunction underlying dementia in these disorders, and support the development of Casp2 inhibitors to treat Lewy body dementia." (PMID 31362787, 2019). "The importance of this result is that it lends support to the potential use of Casp2 inhibitors to ameliorate dementia in LBD." (PMID 31362787, 2019). "Thus, while it has been established that caspase-2 protein levels are elevated in multiple forms of dementia, it is not clear if the increases in the protein levels are regulated at the genetic level through increased transcription, or at the post-translational level." (PMID 36129947, 2022).
glioma (5 papers, 2008 to 2023). A benign or malignant brain and spinal cord tumor that arises from glial cells (astrocytes, oligodendrocytes, ependymal cells). "Few studies have investigated the efficacy of actinomycin D in high grade glioma, although a prior study has indicated that it is effective in glioma cells through the activation of caspase-2 and -3 mediated apoptosis." (PMID 29499065, 2018). "In high-grade (grade 3 and 4) glioma sections, 33.3% and 66.7% of samples were positive for caspase-2, respectively." (PMID 27049919, 2016). "Immunohistological staining of the tissues using a polyclonal caspase-2 antibody showed strong staining in the representative glioma samples." (PMID 27049919, 2016). "Finally, although caspase-2 was identified as a target of miR- 149 in U87 MG cells, it is possible that miR-149 targets other genes in distinct subsets of glioma tumors." (PMID 27049919, 2016). "Besides, the involvement of miR-149 and Caspase-2 in the resistance to temozolomide or cisplatin in glioma was revealed." (PMID 27049919, 2016). "However, the results suggest that the expression level of caspase-2 is proportional depending on the glioma malignancy grade." (PMID 27049919, 2016). "Therefore, our results demonstrate the implication of Caspase 2 in glioma cell death induced by HDACi." (PMID 25275596, 2014). "However, in low-grade (grade 2) glioma sections, 21.3% samples were positive for caspase-2." (PMID 27049919, 2016). "Therefore, HDACi-treated glioma cells die by a mechanism of mitotic catastrophe involving the activation of caspase-2 and the mitochondrial pathway due to DNA-damage accumulation and G2 checkpoint impairment, according to the current concept of mitotic catastrophe." (PMID 25275596, 2014). "By reviewing previous studies, we found that CASP2, NCAPG2, BAZ1B, and ZNF800, the genes most positively related to NUP205, were reported as carcinogenic genes in cancer, especially CASP2, NCAPG2, and BAZ1B, which were found to be carcinogenic genes in glioma." (PMID 37284202, 2023).
Lissencephaly (5 papers, 2018 to 2024). A spectrum of malformations of cortical development caused by insufficient neuronal migration that subsumes the terms agyria, pachygyria and subcortical band heterotopia. "Biallelic truncating variants in CASP2 cause similar neurodevelopmental disorder with lissencephaly, suggesting that the PIDD1–RAIDD-caspase-2 axis is crucial for normal gyration of developing human neocortex as well as cognition and behavior." (PMID 38676703, 2024). "Biallelic truncating mutations in CRADD—the protein bridging PIDD1 and caspase-2—have been reported in intellectual disability (ID), and in a form of lissencephaly." (PMID 33414379, 2021). "Recent whole-exome sequencing study showed that the RAIDD mutations in the death domain (DD), including G128R, F164C, R170C, and R170H mutations, cause thin lissencephaly (TLIS) by reducing caspase-2-mediated neuronal apoptosis." (PMID 30281648, 2018). "Results of a whole-exome sequencing study showed that the RAIDD mutations in the DD, including G128R, F164C, R170C, and R170H mutations, cause thin lissencephaly (TLIS) by reducing caspase-2-mediated neuronal apoptosis." (PMID 30281648, 2018).
liver cancer (5 papers, 2016 to 2022). An epithelial or non-epithelial malignant neoplasm that arises from the liver. "We found that CASP2 and PIDD1 expression is increased in human HCC as well as DEN‐induced murine liver cancer." (PMID 33225610, 2020). "However, in liver cancer cell lines, glutamine deprivation did not induce caspase-9 or -8 activation, but rather stimulated caspase-2 activity." (PMID 27419628, 2016).
prostate carcinoma (5 papers, 2007 to 2014). A carcinoma that arises from epithelial cells of the prostate gland. "Our study also suggests that caspase 2 is a key target in the determination of the susceptibility of prostate cancer cells to PL-induced apoptosis." (PMID 17262078, 2007). "Our present study indicates that caspase 2 is an intracellular target for upregulating the susceptibility of PC3 cells or prostate cancer cells containing a mutated AR to PL-induced apoptosis." (PMID 17262078, 2007). "Our study implies that high doses of PL are able to elicit multiple apoptotic signalling pathways in prostate cancer cells, and that caspase 2, acting downstream of the AR, sensitises prostate cancer cells to PL-induced apoptosis." (PMID 17262078, 2007). "Our results here demonstrate the interconnection between AR and caspase 2 in the regulation of PL-induced apoptosis in prostate cancer cells." (PMID 17262078, 2007). "Encapsulation of DTX in nanoparticles could induce more apoptosis of prostate cancer cells through the activation of the caspase-2 pathway." (PMID 25526569, 2014).
Burkitt lymphoma (4 papers, 2015 to 2018). A rare form of malignant mature B-cell non-Hodgkin lymphoma. "Reduced caspase-2 protein levels have also been reported in a meta-analysis of published data sets for Burkitt lymphoma (BL), mantle cell lymphoma (MCL), chronic lymphocytic leukemia (CLL) and hairy cell leukemia." (PMID 27049919, 2016). "Further, no variation of HLA-DRα was detected in lysates isolated from the Daudi Burkitt’s lymphoma cells treated with the zVAD-fmk pancaspase inhibitor for 72 h, indicating that proteolytic activity of caspase-2, or of other caspases, does not interfere with HLA expression." (PMID 29362422, 2018).
non-small cell lung carcinoma (4 papers, 2013 to 2022). A group of at least three distinct histological types of lung cancer, including non-small cell squamous cell carcinoma, adenocarcinoma, and large cell carcinoma. "It has reported that combrestatin CA-4 induced caspase-2 independent mitotic catastrophe in non-small cell lung cancer cells." (PMID 23762410, 2013). "Moreover, multiple miRNAs including miR-183, miR-494 and miR-182-5p have been shown to function as tumor promoters in non-small cell lung cancer (NSCLC) by inhibiting caspase-2-induced apoptosis." (PMID 36171196, 2022).
COVID-19 (3 papers, 2021 to 2023). A disease caused by infection with severe acute respiratory syndrome coronavirus 2. "CASP2, part of the top 119 proteins, has previously been identified to be upregulated in COVID-19 and cardiomyopathy." (PMID 36809921, 2023). "Caspase 2 (CASP2), also upregulated in COVID-19 and cardiomyopathy, is associated with the downregulation of IFIH, which is capable of recognizing viruses and inducing inflammation." (PMID 34071557, 2021). "Consistent with the apoptosis trend of Tim-3+ NKT cells, an elevated expression level of almost all caspase genes in Tim-3+ NKT cells was observed in controls and patients with mild and severe COVID-19, especially caspase-2, caspase-3, caspase-6, and caspase-9." (PMID 35250975, 2022).
glioblastoma (3 papers, 2014 to 2022). The most malignant astrocytic tumor (WHO grade IV). "To confirm the targeting of miR-149 on caspase-2 expression, we employed A172 cell line, another cultured human glioblastoma cell line." (PMID 27049919, 2016). "Silencing of caspase-2 expression in cultured glioblastoma cells allows the up-regulation of a limited number of genes, among which some are related to cholesterol homeostasis." (PMID 25330190, 2014). "CASP2 deregulation was not significant in either glioblastoma cell line, but it was constantly increasing." (PMID 36142793, 2022).
Insulin resistance (3 papers, 2016 to 2024). Increased resistance towards insulin, that is, diminished effectiveness of insulin in reducing blood glucose levels. "Our data support this concept because caspase-2-deficient mice fed a Western diet were protected from many aspects of the metabolic syndrome, namely increased adiposity, insulin resistance, dyslipidemia and NAFLD development and progression." (PMID 26890135, 2016). "WT mice fed the Western diet developed overt T2DM, with fasting glucose levels of 200 mg/dl, despite increased insulin levels, and HOMA (homeostatic model assessment)-insulin resistance higher than 15, whereas caspase-2-deficient mice maintained normal glucose metabolism." (PMID 26890135, 2016).